INS (insulin)
Diseases named in the same sentence as INS in open-access papers (continued):
Sharing a sentence is not in itself a finding about the gene and the disease.
Insulin resistance (continued). "The recruitment of subjects stratified by insulin sensitivity allowed us to uniquely examine the combined effects of obesity and insulin resistance on glucagon, GLP-1, and GIP secretion, which has not been previously characterized in pediatric studies." (PMID 38087928, 2024). "Systolic and diastolic blood pressure, insulin resistance (measured by HOMA-IR), insulin, HbA1c, fasting blood glucose, total cholesterol, LDL cholesterol, HDL cholesterol and triglycerides, BMI, waist circumference, and fat mass, were all decreased (p < 0.001) following the use of the VLCKD." (PMID 38542785, 2024). "This leads to a condition in which insulin action is defective and a given concentration of insulin fails to trigger glucose uptake signaling, referred to as insulin resistance (IR)." (PMID 38475455, 2024). "With central insulin resistance, the brain cells do not respond, with a decrease in insulin receptors and reduction in the insulin-signaling process." (PMID 39518747, 2024). "In our previous study, we found that it improved hyperglycemia in high-fat diet (HFD)-induced T2DM mice; however, the ability to improve insulin resistance with relatively inadequate insulin secretion is not clear." (PMID 39334959, 2024). "Although some studies have suggested potential roles for vitamins D and K in glucose metabolism and insulin sensitivity, there is limited and inconclusive research on their levels in T2DM patients and their relationship with blood glucose levels and insulin resistance." (PMID 39076511, 2024). "Additionally, a study using rodent models showed that overexpression of PAI-1 in adipocytes led to insulin resistance, while the knockout of PAI-1 in adipocytes improved insulin action." (PMID 38339160, 2024). "The Homeostasis Model Assessment of Insulin Resistance (HOMA-IR) is the most widely used surrogate indicator of IR but has limitations due to its complexity and cost, and it cannot be used in populations receiving insulin therapy." (PMID 39534262, 2024). "Several recent meta-analyses of randomized controlled trials (RCTs) show that pistachios improve fasting blood glucose, insulin, HbA1c, and insulin resistance measured by HOMA-IR compared with no nut interventions." (PMID 38278217, 2024). "A limitation of the current study is the lack of markers of insulin resistance, such as plasma insulin levels." (PMID 38705923, 2024). "Earlier studies have reported that various pathological pathways mediate peripheral insulin resistance without affecting insulin sensitivity." (PMID 38778421, 2024). "Therefore, IR has been primarily evaluated using indices such as the homeostasis model assessment of insulin resistance (HOMA-IR), quantitative insulin-sensitivity check index (QUICKI), 1/fasting insulin, and glucose/insulin ratio (GIR)." (PMID 38539404, 2024). "T1D is primarily managed via insulin to address the lack of endogenous insulin, whilst T2D is often managed via oral and injectable glucose-lowering therapies to address insulin resistance, with medication titration and insulin use as required." (PMID 39691822, 2024). "This study undertook a retrospective analysis of serum progesterone levels, HbA1c, insulin levels, and insulin resistance in GDM patients with and without PROM to assess the likelihood of PROM development in this population." (PMID 39216124, 2024). "Insulin resistance is considered the major mechanism in the development and progression of MASLD/MASH as a result of impaired insulin signaling that leads to increase intracellular fatty acid-derived metabolites such as diacylglycerol, fatty acyl CoA or ceramides." (PMID 39618812, 2024). "Additionally, Rat insulin resistance (HOMA-IR) and insulin concentration ELIZA kit was gained from Invitrogen (USA, Cat." (PMID 39585487, 2024).
Insulin resistance (continued). "By enabling a larger fraction of secreted insulin to reach systemic circulation, reduced ICR may serve as an adaptive mechanism to preserve normal glucose tolerance (NGT) in response to insulin resistance." (PMID 39138690, 2024). "Meanwhile, basal insulin hypersecretion is observed in obese populations even in the absence of insulin resistance, which is correlated with increased plasma lipid." (PMID 38436759, 2024). "Indeed, this observation was accompanied by a significant reduction in fasting insulin and a tendency for improved insulin resistance index (HOMA IR), suggesting increased sensitivity of the insulin-target cells and better metabolic health." (PMID 38337640, 2024). "However, in 3T3-L1 adipocytes, IRF3 contributed to insulin resistance induced by TLR ligands, while IRF3 knockout improved glucose homeostasis by enhancing glucose uptake and increasing GLUT4 expression and insulin signaling in adipose tissue." (PMID 39669992, 2024). "Our findings suggest that alterations to insulin-dependent signalling in the cerebrovascular are not confined to adults who meet clinical thresholds for insulin resistance." (PMID 38914735, 2024). "Moreover, insulin levels exhibited a significant increase in T2DM control rats compared to the control group, indicating the development of insulin resistance." (PMID 39065652, 2024). "The relatively high activities of β-cell PC and the mitochondrial phosphoenolpyruvate (PEP) cycle further confine glucose to pyruvate metabolism in the mitochondria and are beneficial for insulin release, glucose homeostasis, and high fat diet (HFD)-induced insulin resistance." (PMID 38404962, 2024). "The glycogen was detected after stimulating cells with 100 nM insulin, the reduction of glycogen in TNF-α-induced HepG2 and the increase of glycogen in lrisin-treated cells were used to evaluate insulin resistance model and anti-insulin resistance activity of lrisin, respectively." (PMID 39749015, 2024). "To further investigate the potential impact of farrerol on insulin resistance, we conducted GTTs and ITTs to evaluate glucose homoeostasis and insulin sensitivity in mice with or without farrerol supplementation." (PMID 39289804, 2024). "In contrast, the E group found no significant decrease in insulin, insulin resistance indices, HbA1c, total cholesterol, LDL-c, and HDL-c." (PMID 39029066, 2024). "Therefore, the homeostasis model assessment of insulin resistance (HOMA-IR) offers a more straightforward and useful option by measuring insulin and fasting blood glucose." (PMID 38904046, 2024). "Indeed, supraphysiological muscle overexpression of PGC-1α paradoxically induces intramuscular lipid accumulation and insulin resistance in transgenic mice, whereas modest increases (~25%) in PGC-1α protein abundance in muscle promote insulin sensitisation." (PMID 38216792, 2024). "Additionally, we calculated the insulin sensitivity index (ISI) and the homeostasis model assessment of insulin resistance index (HOMA-IR)." (PMID 38665877, 2024). "Furthermore, in response to intracellular and extracellular stresses, the activations of JNK and NF-κB induce insulin resistance through the serine phosphorylation of the insulin receptor substrate (IRS)-1 or IRS-2, subsequently blocking insulin signaling." (PMID 38248467, 2024). "Alternatively, suppressing whole-body BCAA oxidation in mice by deleting PP2Cm increases circulating BCAA and BCKA levels and enhances glucose tolerance and insulin sensitivity, regardless of the presence or absence of obesity and insulin resistance." (PMID 39007094, 2024). "However, the accompanying implication of increased insulin sensitivity, given the CABG donors higher propensity for insulin resistance, seems to counteract this point." (PMID 39595019, 2024).
Insulin resistance (continued). "In comparison with control diets, plant-based diets improved Homeostatic Model Assessment for Insulin Resistance (HOMA-IR) (−0.97, 95% confidence interval (CI) (−1.67, −0.27), p = 0.007) and fasting insulin (−4.13 μU/mL, 95% CI (−7.22, −1.04), p = 0.009) in people with overweight/obesity." (PMID 38999858, 2024). "Postnatally, these animals display impaired pancreatic development with reduced β-cell mass, defective glucose-stimulated insulin secretion (GSIS) and improved insulin sensitivity which transitions to insulin resistance (IR) and glucose intolerance in adulthood." (PMID 38704026, 2024). "Nonetheless, IRI-HOMA primarily gauges hepatic rather than peripheral insulin resistance and, indirectly, insulin sensitivity." (PMID 38792408, 2024). "Additionally, omega-3 improves hepatic insulin sensitivity by improving insulin signaling, which is a key factor of NAFLD prevention and treatment, as insulin resistance is one of the main factors in the development of this disease." (PMID 39458499, 2024). "The main advantage of the TyG index is that it is calculated from fasting glucose and triglycerides and does not require the measurement of serum insulin, thus TyG index is a simple and easy-to-use technique for evaluating insulin resistance." (PMID 38218859, 2024). "Their study revealed that both FBG and insulin levels were significantly higher, and were accompanied by insulin resistance in patients with GDM when compared to non-diabetic control subjects." (PMID 39035597, 2024). "In total, OL mitigated hyperglycemia and increased plasma insulin levels, without affecting the glucose intolerance and insulin resistance." (PMID 39153251, 2024). "Insulin resistance can be evaluated using the homeostatic model assessment of insulin resistance (HOMA-IR), which is calculated from the levels of fasting plasma glucose and immunoreactive insulin (IRI)." (PMID 38771888, 2024). "Insulin signaling can be dysregulated in cumulus cells in obese and infertile women with polycystic ovarian syndrome without recognizable insulin resistance." (PMID 38790245, 2024). "UCSC-EXOs could increase insulin sensitivity by increasing the activation of insulin/AKT signaling pathway and inhibiting the secretion of proinflammatory cytokines like TNF-α, which could reverse insulin resistance in T2DM." (PMID 38720885, 2024). "While HOMA-IR is widely used as a non-invasive method to study insulin resistance, its value diminishes in patients undergoing insulin treatment or those lacking functional β-cells." (PMID 39459383, 2024). "In most metabolic disorders, a lack of insulin or insulin resistance results in a high concentration of blood glucose, known as hyperglycemia." (PMID 39049964, 2024). "Influencing mechanisms may involve insulin, IGF-1, insulin resistance, endogenous hormones, leptin, adiponectin, inflammatory factors and other factors." (PMID 39011481, 2024). "The absolute values of the main outcomes (fasting glucose, insulin, and homeostatic model assessment for insulin resistance) at baseline and 4 and 8 weeks did not significantly differ between trial arms." (PMID 38524210, 2024). "The Homeostatic Model Assessment of Insulin Resistance (HOMA-IR) is a method used to quantify IR and beta-cell function, which is calculated using fasting glucose and insulin levels, providing an estimate of IR that is crucial in understanding the metabolic profile of patients." (PMID 39346096, 2024). "First, as renal function is at a higher level during this period, the decline in eGFR is predominantly characterized by insulin resistance rather than impaired insulin excretion." (PMID 38388456, 2024).
Insulin resistance (continued). "Unlike other IR indices such as the homeostasis model assessment of insulin resistance (HOMA-IR), quantitative insulin sensitivity check index (QUICKI), and homeostasis model assessment of β-cell function (HOMA-β), the TyG index does not require insulin quantification." (PMID 39003471, 2024). "The Ser503Ala mutation disrupts this cellular mechanism, impairing hepatic insulin clearance and thus leading to chronic hyperinsulinemia and ensuing insulin resistance, but without fasting hyperglycemia." (PMID 40808720, 2024). "Insulin spiking and usage were improved by miR-10a/b-5p injection in OVX/HFHSD-fed female mice, indicating that miR-10a/b-5p could reduce insulin resistance." (PMID 39337631, 2024). "The closest associations were seen for C-peptide and the insulin resistance measures, HOMA, TyG-index and the Matsuda index, suggesting a role involving insulin resistance rather than glucose or insulin itself." (PMID 38777863, 2024). "After insulin injection, the blood glucose level in the model group was higher than in other groups at all time points, indicating that the T2DM mice showed symptoms of insulin resistance." (PMID 39334959, 2024). "Betaine administration for 4 weeks to mice with established fatty liver and insulin resistance created by feeding a high fat diet for 14 weeks (i.e., “treatment” studies) led to improvement in glucose tolerance test, ALT, and hepatic insulin signaling pathways." (PMID 39119463, 2024). "Intranasal insulin detemir exerted better action in the hypothalamus and reduced peripheral insulin resistance in individuals who are APOE ε4 negative or obese, as compared to regular insulin." (PMID 38441832, 2024). "SBP showed positive correlations with obesity (BMI, % fat, fat mass, and serum leptin levels) and insulin resistance (insulin and HOMA-IR) factors, and a negative correlation with the insulin sensitivity parameter (QUICKI)." (PMID 39285220, 2024). "Adipokines and relative leukocyte telomere length (RLTL) were measured, and changes in Homeostatic Model Assessment for Insulin Resistance (HOMA-IR), Homeostatic Model Assessment for β-Cell Function (HOMA-β), and Quantitative Insulin Sensitivity Check Index (QUICKI) were calculated." (PMID 38615017, 2024). "HOMA-IR value for NPD was within the insulin-sensitive range (<1.0) except at week 16, while the pups born from the PD group had a significantly higher HOMA-IR value, which was in the range of significant insulin resistance." (PMID 38791468, 2024). "TNF-α is thought to reduce insulin signaling by decreasing the phosphorylation of the insulin receptor substrate-1 (IRS-1) Tyr632 and Akt Ser473, which are downstream effectors of the insulin receptor, thereby resulting in insulin resistance." (PMID 39200235, 2024). "There are limitations in using simple measures to define insulin resistance in youth due to the lack of universally agreed normal ranges for insulin levels, considering the physiological insulin resistance of puberty." (PMID 38958831, 2024). "In contrast, in pregnant women with GDM, insulin secretion fails to compensate for the progressive increase in insulin resistance during pregnancy, leading to the development of maternal hyperglycemia." (PMID 38374136, 2024). "Long-term intake of high-fat diet can lead to weight gain, fat accumulation and elevated blood glucose in diabetic mice, resulting in insulin resistance, which makes the mice endocrine more insulin to maintain normal glucose and lipid metabolism in the body." (PMID 38476942, 2024). "Although the cafeteria diet increased insulin resistance in both sexes, with an increase in HOMA-IR score, female rats maintained glucose levels, while glucose raised significantly in males, consistent with the protective role of estrogens on insulin action." (PMID 38613042, 2024).
Insulin resistance (continued). "Moreover, the values of the homeostatic model assessment for insulin resistance (HOMA‐IR) were significantly lower in DC12 rats as compared with the HFD group, suggesting a higher hepatic insulin sensitivity." (PMID 39600104, 2024). "Also, we showed that the D + AT + HD group had the lowest levels of insulin, glucose, and HOMA-IR (a marker of insulin resistance) among the diabetic groups." (PMID 38494538, 2024). "Adipocyte hypertrophy also inversely correlates with insulin sensitivity in nonobese individuals, suggesting that metabolic dysfunction, rather than obesity, promotes systemic insulin resistance." (PMID 38035802, 2024). "Consistently, L-SACC1 mice developed impaired insulin clearance and, consequently, hyperinsulinemia-driven insulin resistance without affecting pancreatic beta-cell function and insulin secretion." (PMID 40808720, 2024). "Although we did not observe a beneficial effect on glucose tolerance, insulin resistance was remarkably improved, with lower serum insulin levels in the KD group." (PMID 38609395, 2024). "Within the cell, insulin activates insulin receptor substrate (IRS) proteins (IRS-1 to -6) through tyrosine phosphorylation, a crucial step that is disrupted in most cases of insulin resistance." (PMID 38807790, 2024). "The Dietary Approaches to Stop Hypertension (DASH) diet was the most effective in reducing Homeostatic Model Assessment of Insulin Resistance (SUCRA 92.33%), fasting blood glucose (SUCRA 85.92%), fasting insulin level (SUCRA 79.73%) and triglyceride level (SUCRA 82.07%)." (PMID 38388374, 2024). "In Japanese, insulin secretary capacity is much smaller than that of Westerners; that is, the main cause of T2DM is impaired insulin secretion, but not insulin resistance." (PMID 38223524, 2024). "On the other hand, in the case of insulin resistance induced by the use of glucocorticosteroids in transplant recipients, the administration of long-acting basal insulin alone is not an appropriate approach." (PMID 39204092, 2024). "Many hepatic insulin resistance models have been suggested, but a considerable amount of data supports the participation of diacylglycerol (DAG) buildup and protein kinase C epsilon (PKCε) stimulation in damaging hepatic insulin signaling." (PMID 38425436, 2024). "This decrease in the insulin concentration may indicate an improvement in insulin resistance, as assessed by HOMA-IR, which takes into account fasting insulin and glucose values." (PMID 38897385, 2024). "To further investigate the central aspect of insulin resistance, we measured glucose uptake in both treated and non-treated spheroids in the presence and absence of insulin." (PMID 38820505, 2024). "The dams’ glucose handling was measured by assessing insulin sensitivity and beta-cell function through the insulin resistance (HOMA-IR), insulin sensitivity (HOMA-S%), and Beta-cell secretory capacity (HOMA-β%) indices, along with plasma ACTH and corticosterone concentrations." (PMID 38791468, 2024). "Thus, markers of insulin sensitivity (e.g. eGDR) are positively related to ONL and MZ thickness, whereas an impaired glucose tolerance (e.g. HbA1c) and insulin resistance (e.g. HOMA2-IR) are inversely related to ONL and MZ thickness." (PMID 38431705, 2024). "Insulin can increase lipase activity, which increases triglyceride uptake by adipose tissue, promoting fat storage in the liver, and leading to NAFLD and excessive lipid deposition, further exacerbating insulin resistance." (PMID 39135721, 2024). "Given the data of insulin levels are not widely measured, there are several surrogate markers of insulin resistance, of which TyG index is a reliable indicator." (PMID 38812015, 2024). "Furthermore, ethanol impacts the uptake of glucose by increasing peripheral insulin resistance and reducing GLUT4 expression, thus lowering insulin sensitivity and glucose tolerance." (PMID 39275332, 2024).